SAT1 (spermidine/spermine N1-acetyltransferase 1)
Diseases named in the same sentence as SAT1 in open-access papers (continued):
Sharing a sentence is not in itself a finding about the gene and the disease.
Insulin resistance (1 paper, 2021). Increased resistance towards insulin, that is, diminished effectiveness of insulin in reducing blood glucose levels. "SAT1 knockout mice exhibit insulin resistance upon aging, while SAT1 overexpressing mice demonstrate improved glucose tolerance." (PMID 34902085, 2021).
inverted papilloma (1 paper, 2025). An endophytic benign papillary epithelial neoplasm that results from the invagination and proliferation of epithelial cells in the underlying stroma.
lymphoma (1 paper, 2016). A malignant (clonal) proliferation of B- lymphocytes or T- lymphocytes which involves the lymph nodes, bone marrow and/or extranodal sites. "For example, in EBV-positive lymphoma cell clones SAT1 activity is lowered compared with EBV-negative cell clones, which promoted cell growth." (PMID 27283903, 2016).
mastitis (1 paper, 2025). Inflammation of breast tissue during lactation or postpartum due to an obstructed duct or infection. "Notably, the expression levels of HMOX1 and SAT1 were significantly increased in S. aureus-challenged Mac-T cells, and this upregulation was consistent with trends observed in transcriptome data from mother–daughter pairs of cows with subclinical mastitis caused by S. aureus infection." (PMID 40141146, 2025). "Furthermore, the analysis of transcriptomic data from mother–daughter pairs affected by subclinical mastitis demonstrated elevated expression of both SAT1 and HMOX1 in the infected groups compared to the healthy controls." (PMID 40141146, 2025). "Key ferroptosis regulators, such as SAT1 and HMOX1, are proposed as stable molecular markers of mastitis susceptibility, regardless of strain variation." (PMID 40141146, 2025). "First, although RNA-seq data confirmed SAT1 upregulation in subclinical mastitis, direct evidence of ferroptosis in vivo is still lacking." (PMID 40141146, 2025). "Transcriptomic profiling of S. aureus-challenged Mac-T cells showed a progressive increase in DEGs as bacterial strains from low to high SCC and clinical mastitis stimulated the cells, with ferroptosis-related genes (HMOX1, SAT1) consistently upregulated across all stages." (PMID 40141146, 2025).
mood disorder (1 paper, 2010). A cognitive disorder a disturbance in which the person's mood is hypothesized to be the main underlying feature. "Our results identified a significant moderating effect of physical abuse on the association between the SAT1 SNP rs3764885 and mood disorders." (PMID 21152090, 2010). "Another SAT1 SNP, rs1894289, also possessed disease-specific risk alleles in terms of its associations with attempted suicide and mood disorders." (PMID 21152090, 2010). "These two SAT1 SNPs were also significantly associated with mood disorders, where they exhibited a dominant mode of inheritance." (PMID 21152090, 2010). "Individuals with homo/heterozyosity for the G allele in rs3764885 (SAT1) and who were CPA victims had elevated rates of mood disorders." (PMID 21152090, 2010).
periodontal disease (1 paper, 2024). "The significantly low levels of OAZ1 and SAT1 reflect a unique trend of polyamine dysregulation in periodontal disease." (PMID 39408925, 2024).
periodontitis (1 paper, 2024). An acute or chronic inflammatory process that affects the tissues that surround and support the teeth. "This generates reservations for the reliability of OAZ1 and SAT1 as biomarkers for OSCC in patients with concomitant periodontitis and smoking habits." (PMID 39408925, 2024). "Smoking also increased levels of OAZ1 and SAT1 in periodontitis." (PMID 39408925, 2024).
progressive ataxia (1 paper, 2020). "Although the expression of Sat1 and Smox is ubiquitous and their expression was globally ablated, Sat1/Smox deficiency led to strikingly selective damage to the cerebellum and progressive ataxia." (PMID 33054763, 2020).
pterygium (1 paper, 2009). A wedge-shaped fibrovascular lesion arising from the bulbar conjunctiva and extending to the cornea. "Several of the genes expressed most abundantly in excised pterygium, particularly S100A9 and SAT1, have roles in cell migration." (PMID 19956562, 2009). "The most abundant complementary DNAs from pterygium include clusterin, keratins 13 (Krt13) and 4 (Krt4), S100A9/calgranulin B, and spermidine/spermine N1-acetyltransferase (SAT1)." (PMID 19956562, 2009).
pyrexia (1 paper, 2022). "The SAT2 NI group showed a quicker response time to initial elevation (1 dpi) compared to 1.3 and 1.4 days for SAT1 and 3 NI, respectively (p = 0.01) All animals from SAT1 and one animal from SAT3 NI groups, showed a short second peak of pyrexia at 8 dpi that lasted less than one day." (PMID 35927724, 2022).
seminoma (1 paper, 2025). A radiosensitive malignant germ cell tumor found in the testis (especially undescended), and extragonadal sites (anterior mediastinum and pineal gland). "In contrast, PAGE5 and SAT1, predominantly expressed in non-metastatic seminoma, were associated with reduced metastatic potential and a lower likelihood of disease progression." (PMID 41203637, 2025).
shigellosis (1 paper, 2015). Shigellosis is a bacterial infection leading to dysentery and is caused by Shigella, which are small, ubiquitous Gram-negative bacteria belonging to the enterobacteria family. "Shigellosis surveys in Iran conducted from 2008 to 2012 have repeatedly shown that this characteristic Asian pulsotype is prevalent and endemic, and that these strains also possess a similar class 2 integron (dfrA1, sat1), but exhibit variability in their ciprofloxacin susceptibility phenotype." (PMID 28348825, 2015).
Telangiectasia (1 paper, 2019). Telangiectasias refer to small dilated blood vessels located near the surface of the skin or mucous membranes, measuring between 0.5 and 1 millimeter in diameter. "In vitro, over-expression of SAT1 can induce both single-stranded or double-stranded DNA breaks and activate the DNA damage/repair response proteins, such poly(ADP-ribose) polymerase, ataxia telangiectasia mutated, and ataxia telangiectasia and Rad3-related protein." (PMID 31561575, 2019).
tuberculosis (1 paper, 2025). A chronic, recurrent infection caused by the bacterium Mycobacterium tuberculosis. "A bioinformatics study utilizing blood microarray transcriptional datasets identified three ferroptosis-related genes-CHMP5, SAT1, and ZFP36-as potential diagnostic biomarkers for tuberculosis (TB)." (PMID 40565608, 2025).
urea cycle disorder (1 paper, 2022). A genetic inborn error of metabolism characterized by the deficiency of one of the enzymes necessary for the urea cycle. "Glycerol-PBA, an alternative form of PBA for urea cycle disorder therapy, regulated SAT1 protein levels in a similar way." (PMID 35801587, 2022).
tumor (85 papers, 2006 to 2026). "Serine aminotransferase 1 (SAT1) is closely linked to serine metabolism, with abnormal expression associated with tumor development." (PMID 40265021, 2025). "The expression analysis of key genes (PNRC1, HERPUD1, TP53INP2, Tob1, and SAT1), which is typically silenced in various tumour tissues and associated with poor prognosis and short survival time, revealed their upregulation upon 24 h treatment with L1." (PMID 39861074, 2024). "In this study, SAT1 was recognized as a tumor marker associated with unfavorable patient prognosis, and its amplification gave rise to a highly invasive phenotype in TNBC." (PMID 39073262, 2024). "Recently, SAT1 was reported to be associated with the regulating process of ferroptosis in tumor cells." (PMID 38831092, 2024). "There were remarkable associations between the differential expression levels of SAT1 mRNA and age (P = 0.015), tumor grade (P = 4.881e-06), IDH (P = 6.11e-03), radiation therapy (P = 1.738e-04), and histology type (P = 5.288e-08)." (PMID 35227235, 2022). "Immunological analysis revealed that SAT1 inhibition reduces neutrophil recruitment to tumors, consequently impairing angiogenesis and tumor growth, thereby identifying a novel metabolic target for cancer immunotherapy." (PMID 40342932, 2025). "Conversely, SAT1 exerted tumor suppressor properties in B-ALL, by triggering ferroptosis upon stress induced by reactive oxygen species (ROS)." (PMID 40603833, 2025). "To assess the specificity of pentamidine toward SAT1, we treated scrambled and SAT1-depleted tumor organoids with increasing concentrations of pentamidine in the presence of different doses of FOLFIRINOX." (PMID 38547055, 2024). "Since it includes genes such as CHOP, CTSK and SAT1, SFI was associated with the tumor cell apoptosis pathway and ferroptosis pathway." (PMID 38809316, 2024). "SAT1, a key enzyme involved in polyamine catabolism, regulates tumor growth and survival in multiple cancer types." (PMID 38547055, 2024). "Treatment of an orthotopic patient-derived xenograft model with the SAT1 inhibitor pentamidine led to a significant decrease in the tumour burden and an increase in the survival of tumour-bearing mice." (PMID 38429478, 2024). "And upregulated SAT1 in TNBC was verified to facilitate tumor progression through the SAT1/YBX1/mTOR axis." (PMID 39073262, 2024). "They found a significant increase in the expression of polyamine-related genes ODC1, SRM, SMS, SAT1, and spermine oxidase in tumour-affected tissues." (PMID 39408925, 2024). "The knockdown of SAT1 in S2-013 cells led to a significant reduction in the tumour burden in the orthotopic co-implantation model." (PMID 38429478, 2024). "The injection of the SAT1 Tet-on H1299 cells into nude mice and induction of the SAT1 expression in xenograft mice showed a dramatic reduction of tumor growth." (PMID 38539832, 2024). "SAT1 knockdown in S2-013 cells also led to a reduction in cancer cell proliferation, based on Ki-67 staining in tumour sections." (PMID 38429478, 2024). "Further research demonstrated that the expression of SAT1 was repressed in HCC tumor tissues compared with normal liver tissues, which was also demonstrated in our validation test." (PMID 37693905, 2023).
tumor (continued). "Quantitative polymerase chain reactionanalysis of the mRNA expression in U-87 MG and SKOV-3 tumor tissuesfrom 15-treated mice showed the presence of Ptgs2/Nfe2l2/Sat1/Akr1c1/Gpx4 genes correlated with ferroptosis in bothgroups." (PMID 36395526, 2022). "Herein we assessed the role of SAT1 expression in 33 different types of cancer using an independent TCGA dataset, indicating notable differences in SAT1 expression between pan-cancer tumor tissues and matched normal tissues." (PMID 35227235, 2022). "Based on the statistical comparison of gene copy numbers within the genomes of both cancer-prone and -resistant species, we identified novel gene targets linked to tumor predisposition, such as CD52, SAT1 and SUMO." (PMID 35741808, 2022). "Using tumor ex vivo tissue slices and applying stable isotope tracer substrates for the polyamine pathway, we further show that the effect of doxorubicin on SAT1 expression and its activity is the mechanism of increased diacetylspermine." (PMID 36207498, 2022). "With the same significant p-value of 0.007, we also identified the SAT1 gene (higher number of copies in the cancer prone group) as one of the possible targets to be further investigated in the context of tumor onset." (PMID 35741808, 2022). "Tumor measurements, ex vivo slices and in vitro experiments determined that SAT1 expression was directly induced by doxorubicin, thereby resulting in elevated urine diacetylspermine." (PMID 36207498, 2022). "Ex vivo tumor slices revealed that doxorubicin directly increases diacetylspermine production by increasing tumor spermidine/spermine N1-acetyltransferase 1 expression and activity, which was corroborated by elevated polyamine flux." (PMID 36207498, 2022). "Tumor levels of other spermine/spermidine-related metabolites like N1-acetylspermidine, N-acetylspermine and diacetylspermine, as well as SAT1 expression, were significantly elevated in TM98 compared with TM97 mice." (PMID 36207498, 2022). "When overexpressed in tumor cells in xenograft models, SAT1 limits tumor growth through ferroptosis induction, which was later shown to be additionally dependent on the lipoxygenase ALOX12." (PMID 34639222, 2021). "Increased SAT1 activity is reported to increase susceptibility to skin carcinogenesis in a transgenic mouse model, and more recently the upregulation of SAT1 was reported to drive tumor aggressiveness and radiation response." (PMID 34414180, 2021). "The increased expression of SAT1 in GBM was related to the resistance of tumor cells to radiotherapy." (PMID 32733879, 2020). "SAT1 modulates cell migration and resistance in multiple tumor types, whereas PPP2R2D is a component of the tumor-suppressive phosphatase PP2A." (PMID 32029502, 2020). "Some investigations have shown that high level expression of SAT1, display tumor-suppressive effects while other studies point to neoplastic initiator role of SAT1 overexpression." (PMID 23826488, 2013). "According to recent studies, SAT-1 has a contradictory role in neoplastic promotion which is relevant to tumor tissue." (PMID 23826488, 2013). "Indeed, SAT1 overexpression reduced tumor incidence in a prostate cancer model, while increasing it in mice predisposed to intestinal tumor formation." (PMID 40603833, 2025).
tumor (continued). "Furthermore, tumours co-implanted with HPS cells showed increased SAT1 expression, which was abolished by mithramycin." (PMID 38429478, 2024). "Moreover, notable to observe is that this promotion of tumor formation was suppressed by the restoration of SAT1 expression, which is consistent with in vitro experiments." (PMID 38831092, 2024). "The activation of SAT1 expression induces lipid peroxidation and sensitizes cells to undergo ferroptosis upon reactive oxygen species (ROS)-induced stress, which also leads to suppression of tumor growth in xenograft tumor models." (PMID 36778917, 2023). "The RT‐PCR results demonstrated that mRNA expression levels of SLC7A11, SLC1A5, and GCLM were notably up‐regulated and SAT1 was down‐regulated in HCC patients' tumor tissues compared with their ANLTs, which were consistent with the results from TCGA database analysis." (PMID 35841206, 2023). "In addition, SAT1 overexpression in tumor tissues correlates with a higher degree of infiltrating macrophages and CD8+ T cells in tumor mass; however, SAT1 prognostic value depends on a tumor type." (PMID 38203246, 2023). "Activation of SAT1, a rate-limiting enzyme in polyamine catabolism, induced lipid peroxidation and sensitized cells to undergo ferroptosis upon ROS-induced stress, which was found to suppress tumor growth in xenograft tumor models." (PMID 36297287, 2022). "SAT1 is involved in the regulation of ferroptosis, tumor proliferation, migration, and invasion." (PMID 35227235, 2022). "SAT1 also involves in cell migration, proliferation and tumor growth." (PMID 34249910, 2021). "In the exploration of the clinical significance of MNT, we identified a negative association between MNT and SAT1 expression in 150 tumor tissues of LUAD patients, and the same correlation pattern was also observed in 48 tumor tissues from LUAD patients undergoing ACT." (PMID 38831092, 2024). "In addition, doxorubicin induction of SAT1 may initially increase urine diacetylspermine levels in indicating that a patient will respond to treatment, prior to the decrease in tumor volume, as an early marker of treatment effectiveness." (PMID 36207498, 2022). "Therefore, we hypothesized that increased urinary diacetylspermine levels could be a result of tumor SAT1 induction." (PMID 36207498, 2022). "Therefore, it can be speculated that CD44 and SAT1 may regulate immune checkpoints to involve in tumor immunity." (PMID 34249910, 2021). "And knockdown of SAT1 using the cutting‐edge CRISPR‐Cas13 technology effectively abolished the tumor growth inhibition triggered by L14‐8." (PMID 40536697, 2025). "Conversely, tumor cells overexpressing PAGE5 and SAT1 exhibited reduced stemness, migratory capacity and proliferation." (PMID 41203637, 2025). "We next conducted subcutaneous tumor formation by injecting deferent groups of A549 cells (MNT-NC, MNT-OE, MNT-NC + SAT1, MNT-OE + SAT1) into nude mice to validate the results obtained above in vivo." (PMID 38831092, 2024). "Since SAT1 upregulation was related to inferior prognoses of TNBC patients, it should also have a profound effect on tumor behaviors." (PMID 39073262, 2024). "Previous studies have shown SAT1 promotes DNA double-strand break repair by regulating BRCA1 and homologous recombination, aiding in tumor survival." (PMID 36358597, 2022).